ELOVL2 (ELOVL fatty acid elongase 2)
Diseases named in the same sentence as ELOVL2 in open-access papers (continued):
Sharing a sentence is not in itself a finding about the gene and the disease.
tumor (21 papers, 2019 to 2026). "At the single-cell level, ELOVL2 was expressed in tumor cells, cancer associated fibroblasts (CAFs) and smooth muscle cells (SMCs), while PLCG1 was presented in CD4+ and CD8+ T cells, as expected." (PMID 37483592, 2023). "Since the tumor immune status is an another determinant of cancer associated efficacy, we further characterized the immune landscape in the different ELOVL2 subtypes." (PMID 37483592, 2023). "Here, an increased ELOVL2 expression (score ≥ 8) was identified as a strong risk factor for tumor relapse in both uni- (HR: 2.42, 95%CI 1.18–4.94; p = 0.015) and multivariate (HR: 2.09, 95%CI 1.01–4.44; p = 0.046) analyses." (PMID 35445910, 2022). "Intriguingly, preliminary studies have suggested that ELOVL2 deficiency may function as a tumor suppressor in certain contexts, particularly in attenuating tamoxifen resistance through distinct molecular mechanisms." (PMID 40552308, 2025). "The authors examined the relationship between ELOVL2 expression and metastatic relapse-free in a BC cohort with a follow-up of ten years, resulting in the discovery of an association between lower ELOVL2 expression levels and shorter metastasis-free survival and higher tumor grade." (PMID 34572770, 2021). "The expression levels of key enzymes involved in unsaturated fatty acid metabolism (Fads2, Elovl5, Fads1, Elovl2) were significantly altered in the liver and tumor tissues of the HUFA-gavaged mice." (PMID 39941731, 2025). "This duality suggests that ELOVL2’s role is highly influenced by the tumor microenvironment and cancer type." (PMID 40552308, 2025). "The function of ELOVL2 in cancer appears to be context-dependent, with studies reporting both tumor-suppressive and oncogenic roles." (PMID 40552308, 2025). "IHC analysis of archived paraffin-embedded PCa specimens (n = 9) revealed significantly higher ELOVL2 expression in tumor tissues, particularly in enzalutamide-resistant cases, whereas adjacent non-tumorous tissues showed minimal expression." (PMID 40552308, 2025). "Considering the dysregulation of immune status and metabolism remodeling involved in RPLS, we discovered that ELOVL2 played an essential role in tumor progression and even dedifferentiation, and served as the only one lipid metabolism related target biomarker." (PMID 37483592, 2023). "Strikingly, in addition to having tumor suppressor activity, ELOVL2 was shown to recover tamoxifen sensitivity up to 70% in the MCF-7/tamoxifen resistance cells and in a xenograft mouse model." (PMID 37483592, 2023). "Within the GBM tumor, there was a positive correlation of expression of only ELOVL2 in the tumor core with the enhancing tumor region." (PMID 36291290, 2022). "The ELOVL2 expression in the tumor core was positively correlated with the ELOVL1 expression from the enhancing tumor region." (PMID 36291290, 2022). "In contrast, the ELOVL2 expression in the women was lower in GBM tumors (enhancing tumor region—p = 0.02; tumor core—p = 0.004) than in the peritumoral area." (PMID 36291290, 2022). "Increased ELOVL2 expression (score ≥ 8) correlated with tumor relapse in both uni- (HR: 2.42, 95%CI 1.18–4.94; p = .015) and multivariate (HR: 2.09, 95%CI 1.01–4.44; p = .046) analyses." (PMID 35445910, 2022). "Correlations between recurrence and TRIM58, FAM84B, and ELOVL2 expression were analyzed in univariate analyses as well as in multivariate tests adjusted for age, sex, tumor location, extent of resection, and, most notably, histology." (PMID 35445910, 2022). "The same correlation was also found in men, i.e., BMI vs. ELOVL5 and ELOVL6 expressions in the enhancing tumor region and the ELOVL2 expression in the tumor core." (PMID 36291290, 2022). "In the enhancing tumor region, the expression of ELOVL2 in the women was lower than in the peritumoral area (p = 0.04)." (PMID 36291290, 2022). "In the men, the expression level of ELOVL2 was the same in all the examined regions of the GBM tumor." (PMID 36291290, 2022).
tumor (continued). "Here, significantly increased mRNA levels of ELOVL5 were found in tumor tissue, which corresponded with increased calculated ELOVL2/5 activity." (PMID 34206240, 2021). "Many of these proteins (FABP7, FASN and ELOVL2) are up-regulated in GBM patient-derived tumor stem cell cultures compared to more-differentiated adherent cells cultured in serum-containing medium." (PMID 34444824, 2021). "The repression of ELOVL2 by the MYCN and PRC1 complex indicates PRC1 complex inhibition as a potential novel strategy to activate ELOVL2 tumor suppressive functions." (PMID 31856871, 2019). "Analysis of mouse xenografts using SK-N-AS cells that stably expressed shRNA targeting ELOVL2 showed that knockdown of ELOVL2 significantly enhanced tumor volume, mass and decreased the DHA content compared to those in the nontargeting control group." (PMID 31856871, 2019). "The correlation between ELOVL2 overexpression and molecular signatures of extracellular vesicles suggests that formation and release of extracellular vesicles is one of the cell processes by which ELOVL2 controls GBM tumor development." (PMID 31619292, 2019). "Mouse xenograft results showed that enforced ELOVL2 expression diminished the promotion effect of MYCN on tumor growth, mass and re-raised the DHA content in tumors." (PMID 31856871, 2019). "Mouse xenograft results further showed that ELOVL2 knockdown again re-enhanced tumor growth, mass and re-decreased the DHA content in tumors." (PMID 31856871, 2019). "This stage-specific downregulation of ELOVL2 may indicate a shift in PUFA elongation dynamics with tumor progression, potentially affecting the availability of specific longer PUFA required for membrane structure and function." (PMID 40244177, 2025). "Particularly in PCa, ELOVL2 demonstrates a unique tumor-suppressive function, where its high expression is associated with favorable clinical outcomes, while its knockdown enhances malignant phenotypes including proliferation, migration, and invasion in PCa cells." (PMID 40552308, 2025). "ESR1-YAP1 cistromic-transcriptomic overlap also revealed enrichment of ELOVL2, a tumor suppressor in tamoxifen-resistant settings, which emphasizes the need for further investigation in how tumor suppressors may be functioning in fusion-dependent contexts." (PMID 39207954, 2024). "In summary, our study identified ELOVL2 as the potential effective target for RPLS, and patients with LMS2 tumor indicated an immune-excluded phenotype might benefit more from small molecule inhibition targerted ELOVL2." (PMID 37483592, 2023). "ELOVL2 expression was also associated with a > twofold risk of tumor relapse independent of the WHO grade of the tumor." (PMID 35445910, 2022). "Additionally, the ELOVL3 expression in the tumor core was positively correlated with the ELOVL5 expression from the enhancing tumor region and negatively correlated with the ELOVL2 expression from the enhancing tumor region." (PMID 36291290, 2022). "Additionally, there was a positive correlation in the ELOVL2 expression in the tumor core with the ELOVL6 expression in the enhancing tumor region." (PMID 36291290, 2022). "Remarkably, ELOVL2 has been proposed as both a tumor suppressor and, vice versa, a proto-oncogene." (PMID 35445910, 2022). "We also observed subclonal copy gain of KRAS in all 8 samples, as well as subclonal copy loss of both ELOVL2 and IRF4, all of which have been identified in tumours although the effect of these copy number losses in AML is unknown." (PMID 31645898, 2019). "Notably, we show that ELOVL2 knockdown in PDC decreases tumor growth in vivo." (PMID 31619292, 2019). "In the literature, the function of ELOVL2 in tumor cells remains unclear and controversial." (PMID 31856871, 2019). "Overexpression of ELOVL2 and ELOVL5 in para-tumor tissue demonstrates the production of ARA, which is necessary for the generation of signaling and inflammatory lipids." (PMID 39145825, 2025).
tumor (continued). "This study examines the expression of elongases ELOVL1, ELOVL2, ELOVL3, ELOVL4, ELOVL5, ELOVL6, and ELOVL7 in GBM tumor samples from 28 patients (16 men and 12 women), using a quantitative real-time polymerase chain reaction (qRT-PCR)." (PMID 36291290, 2022). "At the same time, the expression of ELOVL2 and ELOVL5 in the enhancing tumor region in women negatively correlated with their age." (PMID 36291290, 2022). "In the men, the expression of the elongases positively correlated with BMI —in particular, the ELOVL2 expression in the peritumoral area and tumor core, and ELOVL5 and ELOVL6 expressions in the enhancing tumor region." (PMID 36291290, 2022). "We showed that the expression of ELOVL2, ELOVL5, and ELOVL6 in the GBM tumor was lower in women than in men." (PMID 36291290, 2022). "We further unravelled that the DHA synesis enzyme ELOVL2 was remarkably upregulated after MYCN depletion and its tumor suppressive properties in this childhood malignancy both in vitro and in vivo." (PMID 31856871, 2019). "There was a negative correlation in the ELOVL2 expression in the enhancing tumor region with the ELOVL3 expression in the tumor core." (PMID 36291290, 2022). "The ELOVL3 expression in the same region of the GBM was not correlated with other elongases except for the ELOVL2 expression in the enhancing tumor region." (PMID 36291290, 2022). "Additionally, the expression of ELOVL2 and ELOVL5 in the enhancing tumor region negatively correlated with age in the women." (PMID 36291290, 2022). "The tumor suppressive properties of DHA and ELOVL2 are repressed by the MYCN and PRC1 jointly, which suggests a new epigenetic mechanism of MYCN-mediated fatty acid regulation and indicates PRC1 inhibition as a potential novel strategy to activate ELOVL2 suppressive functions." (PMID 31856871, 2019). "In the tumor core, the expression of ELOVL3 had a negative correlation with body weight and BMI, while in the peritumoral area, there was a negative correlation between the ELOVL2 expression and height and a negative correlation between the ELOVL4 expression and cigarette pack-years." (PMID 36291290, 2022).
cancer (13 papers, 2019 to 2026). A tumor composed of atypical neoplastic, often pleomorphic cells that invade other tissues. "Some methylation changes associated with aging are predictable, such as methylation of ELOVL2, which is considered one of the most robust biomarkers associated with age, and methylation profiles differ between aging and cancer." (PMID 35992328, 2022). "However, the ultimate mechanisms that are responsible for cancer-associated decreased expression of ELOVL2 remain to be understood." (PMID 30949448, 2019). "Functional studies demonstrated that targeted inhibition of ELOVL2 significantly suppressed cancer cell proliferation and restored enzalutamide sensitivity in resistant cells." (PMID 40552308, 2025). "Beyond its fundamental enzymatic function, emerging evidence reveals that dysregulation of ELOVL2 expression exhibits context-dependent and often paradoxical roles in tumorigenesis across different cancer types." (PMID 40552308, 2025). "Functional validation was performed through targeted inhibition of the elongation of very-long chain fatty acid protein 2 (ELOVL2), followed by assays to assess cancer cell proliferation and enzalutamide sensitivity." (PMID 40552308, 2025). "The stem cell TF SOX2 can bind to the ELOVL2 superenhancer in GSCs to drive the expression of ELOVL2, which is critical for the maintenance of cancer stem cells." (PMID 36720920, 2023). "By way of addition, the overall survival of the patients with lower level of ELOVL2 (by median) in a pan-cancer analysis was worse than that of the counterpart group." (PMID 30949448, 2019). "Further studies are warranted to address the remaining limitations and extend our understanding on the role of ELOVL2 in cancer." (PMID 30949448, 2019). "Notably, a 2022 study revealed that ELOVL2 is significantly upregulated in PCa compared to normal prostate tissue and regulates cancer cell behavior through INPP4B signaling, further underscoring its importance in PCa progression." (PMID 40552308, 2025). "However, further research was still needed to fully elucidate the functions of ELOVL2 in normal cells and its potential implications for cancer treatment." (PMID 37483592, 2023). "ELOVL2-depleted cancer cells exhibited a more malignant phenotype than that of the control group." (PMID 30949448, 2019). "The mRNA levels of ELOVL4 and 5, as well as FADS2 were higher in cancer cells than in normal colon cells, but we did not detected the expression of ELOVL2 and FADS1 in these cells." (PMID 32029824, 2020). "The mRNA levels of ELOVL4, ELOVL5 and FADS2 were increased in cultured cancer cells comparing to normal colon cells, but we did not detected the expression of ELOVL2 and FADS1 in these cells." (PMID 32029824, 2020). "Additionally, ELOVL2 has not been known to be involved in any hallmarks of cancer with respect to our text mining result using Cancer Hallmark Analytics Tool." (PMID 30949448, 2019).
infection (2 papers, 2021 to 2022). The state of being infected such as from the introduction of a foreign agent such as serum, vaccine, antigenic substance or organism. "ELOVL2 was also negatively correlated with deoxyguanosine and dihydroorotate (DNA replication) as well as citramalate, citrulline, creatinine, and S-carboxymethylcysteine, which have all been implicated as being anti-inflammatory in infection (59, –, 61)." (PMID 36453940, 2022).
metabolic disease (2 papers, 2016 to 2023). A congenital disorder (due to inherited enzyme abnormality) or acquired (due to failure of a metabolically important organ) disorder resulting from an abnormal metabolic process. "Also, fatty acid elongation has been implicated in metabolic disease, as exemplified by variation in fatty acid elongase 2 (Elovl2), which has been linked to reduced expression of the enzyme, diminished production of unsaturated fatty acids and a higher BMI." (PMID 37781111, 2023).
ELOVL2 also shares sentences with these, for which no sentence is quoted: type 2 diabetes (3 papers); autism spectrum disorder (2); neurodegenerative disease (2); atopic eczema (1); blood cancers (1); clear cell renal cell carcinoma (1); cognitive decline (1); glaucoma (1); Graves disease (1); hyperlipidemia (1); Insulin resistance (1); nephrotic syndrome (1); nonalcoholic fatty liver disease (1); steatosis (1); uveal melanoma (1); viral infection (1).